ABCG2 (ATP binding cassette subfamily G member 2 (JR blood group))
Diseases named in the same sentence as ABCG2 in open-access papers (continued):
Sharing a sentence is not in itself a finding about the gene and the disease.
tumor (772 papers, 2002 to 2026). "In particular, the transporters encoded by ABCB1 (MDR1/P-gp), ABCC1 (MRP1), and ABCG2 (BCRP) play crucial roles in pumping numerous chemotherapy drugs out of the cell, thus limiting intracellular drug accumulation and enabling tumor cell survival." (PMID 41557172, 2026). "Immune infiltration analysis further demonstrated a positive correlation between ABCG2 expression and endothelial cell infiltration (p < 0.05), a process linked to angiogenesis and enhanced tumor invasiveness." (PMID 40282409, 2025). "In tumour cells, ABCG2 causes resistance to several anticancer medications; however, in normal cells, ABCG2 appears to protect cells against cytotoxic substances." (PMID 40640196, 2025). "A study published only in abstract form using RNA profiling of circulating tumor and invasive cells in 33 patients suggested that high ABCG2 gene expression was associated with shorter PFS on treatment with GemNab." (PMID 40548120, 2025). "Various ABC transporters, particularly ATP‐binding cassette B1/P‐glycoprotein (ABCB1/P‐gp, MDR1) and breast cancer resistance protein (ABCG2), have been implicated in tumor chemotherapy resistance." (PMID 40789057, 2025). "ABCG2, a multidrug resistance protein, was potentially associated with treatment resistance in tumor cells." (PMID 40688093, 2025). "Gain-and loss-of-function experiments suggested that ABCG2 can promote the expression of stem cell marker proteins, inhibit cell apoptosis, and promote tumor progression." (PMID 40370575, 2025). "This association underscores the potential of ABCG2 as a prognostic biomarker, enabling more personalized treatment approaches based on the molecular characteristics of the tumor." (PMID 38542090, 2024). "Still, the percentage of ABCG2-positive tumor cells was significantly associated with Ki67 expression (R2 = 0.07, p = 0.002, r = 0.28)." (PMID 38542090, 2024). "Both ABCG2 expression and the percentage of ABCG2-positive tumor cells were significantly associated with Ki67 expression." (PMID 38542090, 2024). "ABCC2 and ABCG2 are two members of the ABC transporter family that have been widely identified in tumor cells and have been associated with response to therapy and disease prognosis." (PMID 38612927, 2024). "CSCs, identified by their ABCG2 expression, have been implicated in tumor recurrence and poor prognosis, which underlines their clinical significance as a biomarker." (PMID 38542090, 2024). "Studies have also found that ABCG2 rs2231142 genotypes GT + TT were associated with increased exposure to sunitinib in people with neoplasms and increased plasma concentrations of rosuvastatin compared to genotype GG." (PMID 37420302, 2023). "The human body contains 48 ABC transporters, with ABCB1, ABCC1, and ABCG2 being closely associated with tumor MDR." (PMID 38067428, 2023). "Our result that ABCG2 nonsynonymous rs2231142 was associated with tumor response to platinum-based chemotherapy is parallel in several lines to both laboratory findings and population observations." (PMID 33531973, 2021). "ABCG2 is a membrane transporter protein that has been associated with multidrug resistance phenotype and tumor development." (PMID 34356084, 2021). "We found that ABCG2 expression was significantly associated with tumor size (6.1 cm ± 2.7 cm vs. 3.9 cm ± 1.5 cm, p = 0.01) and the response to chemotherapy (62.4% ± 25.1% vs. 75.3% ± 18.7%, p = 0.02)." (PMID 33509236, 2021). "A previous study also reported that patients with the dual expression of CD133 and ABCG2 are at higher risk for tumor recurrence." (PMID 32991066, 2020). "ABCB1 and ABCG2 are the most basic multidrug resistance protein in different tumor tissues, ABCB1 encodes p-gp, and ABCG2 encodes BCRP." (PMID 32258043, 2020). "Previous studies have shown that the ABCG2 C421A polymorphism varies widely among different tumor types and populations." (PMID 29340035, 2017).
tumor (continued). "Overexpression of ABCB1, ABCC1 and ABCG2 in tumor tissues is considered a major cause of limited efficacy of anticancer drugs." (PMID 27689338, 2016). "In conclusion, here, we provide validated results to guide future studies on the associations between ABCG2 immunoreactivity in tumor cells and the benefits of chemotherapeutic treatment in patients with CRC." (PMID 27257141, 2016). "Our results suggested that the upregulation of ABCG2 is likely one of the mechanisms that underlies BDNF-induced tumor resistance." (PMID 27852063, 2016). "Overexpression of ABCB1, ABCC1 and/or ABCG2 in tumor tissues is considered a major cause of limited efficacy of anticancer drugs." (PMID 27689338, 2016). "We observed that the distribution frequency of ABCG2 G34A genotype was associated with tumor clinical stages." (PMID 26634205, 2015). "To date, no data on mutations in the potential substrate binding pocket of ABCG2 in tumor tissue are available." (PMID 23467750, 2013). "Numerous lines of evidence suggest that ABCG2 can be associated with the presence of tumor stem cells and correlates with chemoresistence and a poor prognosis in several human neoplasias." (PMID 23976904, 2013). "Average immunostaining intensity scores for ABCG2 were shown to be associated with early invasive stage, pTa (n = 87) versus pT1 (n = 61), and increasing tumour grade, low grade (n = 93) versus high grade (n = 55) (p<0.05)." (PMID 23226356, 2012). "Furthermore, the ABCG2 profile was significantly associated with progression to the higher grade of the tumor (R2 = 0.05, p = 0.007, r = 0.22), tumor grade (R2 = 0.07, p = 0.0008, r = 0.28), as well as Ki67 expression (R2 = 0.03, p = 0.04, r = 0.18)." (PMID 38542090, 2024). "Therefore, ABCG2 status has a significant impact on tumor initiation and progression, the risk of local recurrence and metastasis to another part of the body, and patient survival." (PMID 39457707, 2024). "Furthermore, the ABCG2 profile was significantly associated with disease progression (p = 0.007, r = 0.23), tumor grade (p = 0.0002, r = 0.31), and Ki67 expression (p = 0.0004, r = 0.31)." (PMID 38542090, 2024). "ABCG2-positive tumor cells only showed association with Ki67 expression (p = 0.002, r = 0.28)." (PMID 38542090, 2024). "ATRX mutations may contribute to a tumor microenvironment that favors the expression of drug resistance genes, including ABCG2." (PMID 38542090, 2024). "Additionally, both ABCG2 profile and score were shown to be moderately associated with tumor progression, while the percentage of ABCG2-positive tumor cells was shown to be a weak indicator of tumor progression." (PMID 38542090, 2024). "Moreover, in the solid variant of PTC, high ABCC1 expression was associated with larger tumor size, while high ABCG2 expression was correlated with lymphovascular invasion." (PMID 35837087, 2022). "The present study firstly detected the expression pattern of p75ICD and compared it to the p75NTR FL in LSCC, and revealed that p75ICD was particularly upregulated in neoplastic squamous cells expressing ABCG2 and was strongly associated with tumor progression." (PMID 35681602, 2022). "Only sparse information is available on ABCG2 minor variants in connection with tumor drug therapy." (PMID 33801813, 2021). "Acquired resistance can be multifaceted because a patient’s tumor may have developed multidrug resistance through ABCG2 or through mutation of TOP1." (PMID 33196706, 2020). "Among the 281 DMET variants that were significantly associated with tumor necrosis, was gene ABCG2." (PMID 30991985, 2019). "The expression levels of ALDH1 and ABCG2 were associated with tumor stages." (PMID 31516883, 2018). "EGFR and KRAS mutation, expression of EGFR family members and of cMET and PTEN and EGFR and ABCG2 germline polymorphisms were tested on tumor tissue or blood samples to either confirm previously proposed predictive role or describe it in an explorative setting." (PMID 28915692, 2017).
tumor (continued). "It has been hypothesized that the mechanisms underlying tumor proliferation by ABCG2 may include activation of PI3K/Akt and STAT3 signaling pathways." (PMID 26064420, 2015). "Also noted were marked decreases in tumor volume, vascularity and proliferative index, associated with the downregulation of HIF1α and ABCG2, and increased intracellular concentrations of active topotecan." (PMID 26623560, 2015). "Furthermore, the ABCG2 profile (r = 0.31, p = 0.0002), chemotherapy (r = 0.58, p < 0.0001), Ki67 expression (r = 0.69, p < 0.0001), tumor progression (r = 0.48, p < 0.0001), and radiotherapy (r = 0.50, p < 0.0001) showed a strong association with tumor grade." (PMID 38542090, 2024). "On one hand, this ABCG2 variant results in elevated cellular retention of folate, which is a rate limiting factor for prostate cancer cell proliferation, thus leading to higher risk for tumor reoccurrence after prostatectomy in patients, who received no drug treatment." (PMID 33801813, 2021). "Consequently, anticancer therapy could eliminate the majority of tumor cells, generate clonal selection of aggressive tumor cells overexpressing ABCG2 and cause their relapse." (PMID 25474134, 2014). "ABCG2 and V-ATPase expression may be strongly associated with drug resistance and tumor metastasis." (PMID 23244569, 2012). "The phenomenon that a low grade tumor has a low expression and that the high grade form of the tumor has high expression levels indicates that the expression rates of ABCG2 and its intensity of staining may be closely associated with the differentiation state of the tumor." (PMID 23244569, 2012). "Many phytochemicals also sensitize CSCs to chemotherapeutic agents by downregulating drug-efflux transporters (e.g., ABCB1, ABCG2) and lowering survival thresholds, resulting in enhanced apoptosis and reduced tumor-initiating potential." (PMID 41595749, 2026). "Taken together, our results suggested that p38 modulated the tumor cell sensitivity to chemotherapeutic agents by regulating the efflux function of ABCG2." (PMID 41541684, 2026). "These divergent findings highlight the complexity of the function of p38 and underscore the need to clarify its specific role in regulating ABCG2-mediated drug resistance in tumor cells." (PMID 41541684, 2026). "Inhibiting p38 phosphorylation decreased the efflux of chemotherapeutic drugs in tumor cells by downregulating the formation of ABCG2 oligomers on the cell membrane." (PMID 41541684, 2026). "We assessed drug sensitivity and identified ABCG2 as broadly overexpressed across tumor types and negatively correlated with chemosensitivity." (PMID 41541684, 2026). "Breast cancer resistance protein (ABCG2) significantly contributes to decreased sensitivity of tumor cells to chemotherapy." (PMID 41541684, 2026). "Both our previous and current studies have proved that inhibiting the efflux function of ABCG2 improved the cytotoxic effects of chemotherapy drugs on tumor cells." (PMID 41541684, 2026). "In our study, we discovered that p38 was correlated with reduced sensitivity of tumor cells that overexpress ABCG2 to multiple chemotherapeutic agents." (PMID 41541684, 2026). "Similar enhancement of cytotoxicity was observed in multicellular tumor spheroids, where tinodasertib reduced the spheroid growth when combined with ABCG2 substrates (p < 0.05)." (PMID 40584625, 2025). "In agreement with in vitro data, axitinib significantly potentiated the anti-tumor activity of topotecan in nude mice bearing ABCG2-overexpressing tumor xenografts." (PMID 41154409, 2025). "Various chemical classes of antimalarials exhibit anticancer activity, can reverse tumor cell resistance to treatment and inhibit the activity of P-gp and/or ABCG2." (PMID 40508176, 2025). "In some cases it has been shown that the expression of ABCB1 and ABCG2 can also increase over time in these tumor cells." (PMID 40893689, 2025).
tumor (continued). "A feed-forward effect was observed: CSC-conditioned neutrophils can reinforce the stemness of melanoma cells, increasing their ability to form tumor spheres and the level of resistance markers (e.g., ABCG2 pump)." (PMID 40806546, 2025). "Members such as ABCB1 (MDR1), ABCC1 (MRP1), and ABCG2 (BCRP) are frequently overexpressed in drug-resistant tumours and CSC subpopulations." (PMID 41321388, 2025). "ABCG2 actively removes various PSs from tumor cells, including Ce6, which can reduce the effectiveness of PDT." (PMID 40943558, 2025). "TLR3 activation in tumor spheres by poly (A:U) induced ABCG2, a marker of drug resistance, which was reduced by the addition of ASA and MF." (PMID 40647457, 2025). "Among these, ABCG2 stands out as a pivotal multidrug-resistant transporter, contributing not only to chemoresistance but also to tumour progression." (PMID 41321388, 2025). "Multidrug resistance in tumor cells is associated with the overexpression of ATP-binding cassette (ABC) transporters, and ART can reverse tumor resistance by downregulating the expression of ATP-binding cassette subfamily G member 2 (ABCG2)." (PMID 40142963, 2025). "ABCG2 serves as a drug efflux transporter and plays a significant role in tumor multidrug resistance and stemness maintenance." (PMID 40370575, 2025). "For example, a study analyzed the expression of seven markers (ALDH1A1, ABCG2, various variants of CD44, CD133, CD271, and Nestin) in 40 cell cultures of primary strains and 40 tumor fragments, making a comparison with normal melanocytes and fibroblasts." (PMID 40806546, 2025). "In ovarian cancer, preclinical studies demonstrate that gold NPs suppress cisplatin-induced EMT and stemness in A2780 and SKOV3 models, reducing MDR1/ABCG2 expression and sensitising tumours to platinum chemotherapy." (PMID 40867257, 2025). "P-glycoprotein (ABCB1, also known as MDR1) and Breast Cancer Resistance Protein (ABCG2) are efflux pumps that limit oral drug absorption in the gut and actively extrude drugs from cells (including at the blood–brain barrier and tumor cells)." (PMID 41295218, 2025). "This is not only because of the impact of ABCB1/ABCG2 activity in the BBB, but also because of ABC transporter-mediated multidrug resistance potentially occurring in tumor cells themselves." (PMID 40893689, 2025). "In this study, we have evaluated the role of ER and RSL3 in sensitizing both ABCB1- and ABCG2-expressing human tumor cells to Adriamycin and Topotecan." (PMID 39859349, 2025). "Abcg2 is expressed in both stromal and tumor cells and allows Abcg2-CreER to promote cell-cycle reentry and proliferation, thus influencing their regenerative properties cSPCs have shown to differentiate into CM via co-culture with CM or alone." (PMID 40928598, 2025). "HBO reduced ABCG2 expression, thereby inhibiting tumor cell stemness and drug efflux to increase chemotherapy sensitivity." (PMID 40370575, 2025). "This subtype exhibited significant stem cell-like characteristics, marked by the high expression of key stemness genes such as EZH2, LGR5, NOTCH1, and ABCG2, which together formed a core regulatory network maintaining tumor stem cell properties." (PMID 40787449, 2025). "Among these, ATP-binding cassette (ABC) transporters—particularly ABCG2—are known to mediate the efflux of TS from tumor cells, thereby reducing intracellular drug retention." (PMID 40284018, 2025). "A recent report showed that tumor cell lines with high levels of ABCG2 expression were more resistant to PDT when free PS chlorine e6 (Ce6) was employed." (PMID 38612619, 2024). "Clinical studies indicate that high expression of ABCG2 in tumours is a prognostic marker for poor clinical outcomes." (PMID 39766280, 2024). "It is suggested that ABC transmembrane transporters (ABCB1, P-gp, MDR1, ABCCs, ABCG2, and MXR) can contribute to the efflux of various drugs from tumor cells." (PMID 38360641, 2024).
tumor (continued). "Overall, the enhanced fluorescence is associated with low expression of ferrochelatase, overexpression of ABCB6, low expression of ABCG2, the accumulation of heme synthesis-related metabolites caused by IDH1 mutations, and the tumor microenvironment." (PMID 39518115, 2024). "Studies demonstrated that higher levels of ABCG2 correlate not only with a more aggressive tumor phenotype but also with poorer patient survival rates." (PMID 38542090, 2024). "IHC analysis in these models showed that the modulation of ABCG2 expression affects drug distribution within the tumor and the surrounding brain tissue, impacting the efficacy of chemotherapeutic agents." (PMID 38542090, 2024). "ABCG2 protein (rs4148153, rs4148155) is one of the UA transporter proteins, and its increase in tumor cells leads to the resistance to multiple drugs." (PMID 38965453, 2024). "The expression of PMI and ABCG2 in tumor tissues was assessed using immunofluorescence and western blot analyses." (PMID 38576495, 2024). "For example, using ATP binding cassette subfamily G member 2 (ABCG2) inhibitors with SG has been effective in overcoming resistance to SN-38 in various neoplasms." (PMID 39768216, 2024). "The expression of ABCG2 in the endothelial cells of blood vessels can limit the delivery of chemotherapeutic drugs to the tumor microenvironment, affecting treatment efficacy." (PMID 38542090, 2024). "Both tumor hypoxia and the number of TSD+ EpCAM+/ABCG2+ CSCs were increased significantly in the cisplatin++ group between the 2nd and 8th weeks of tumor growth." (PMID 39963656, 2024). "The combination of IL-7 with DDP induces NSCLC tumour regression while reducing ABCG2 levels in tumour tissue." (PMID 38675377, 2024). "Our in vivo results indicate that the inhibition of HIFs by FM19G11, as well as its downstream effectors of the pathway, VEGF/VEGFR1 autocrine loop, and EGF/EGFR autocrine loop markedly reduced tumor growth as well as the expansion of the EpCAM+/ABCG2+ cells." (PMID 39963656, 2024). "Studies utilizing IHC have demonstrated a correlation between high ABCG2 expression and increased tumor grade, particularly in CSCs and the tumor vasculature." (PMID 38542090, 2024). "ABCG2 is expressed not only in tumor cells but also on the luminal surface of brain capillary endothelial cells within and surrounding the tumor." (PMID 38542090, 2024). "We also found that the presence of CD44+ALDH1+ABCG2+ tumor cells steadily increased over time (p < 0.001)." (PMID 38534924, 2024). "Decreased Lef1 expression/Re-sensitized tumor cells to docetaxel/Downregulated ABCG2, Vim and Cav1 expression." (PMID 39712006, 2024). "Overexpression of circ0008253 increases cell viability, tumor size, and ABCG2 levels, while reducing OXA sensitivity." (PMID 39703839, 2024). "High expression of BCRP/ABCG2 can affect the absorption, distribution, and metabolism of tumor drugs, and can even result in excretion of tumor drugs, directly leading to drug resistance." (PMID 38324023, 2024). "Nevertheless, it should be emphasized that the expression profile of the ABCG2 in primary tumor tissues differs significantly from that observed in cell cultures." (PMID 39457707, 2024). "ABCG2 is considered a marker of CSCs, which are thought to be responsible for tumor initiation, metastasis, and resistance to therapy." (PMID 38542090, 2024). "One study has found that resistance to DOX therapy fails to eradicate anaplastic thyroid cancer or even to stop tumor progress was closely related to adenosine triphosphate-binding cassette subfamily G member 2 (ABCG2)." (PMID 37919637, 2023). "One of the underlying mechanisms in tumor resistance is the aberrant activation of PI3K/AKT pathways that upregulates the expression of ABC transporters (P-gp/ABCB1, MRP1/ABCC1, and BRCP/ABCG2), and pro-survival molecules such as Bcl-2 and IAPs." (PMID 37627134, 2023).